MEP1A (meprin A subunit alpha)
Synonyms: PPHA
Tractability: Small molecule: a structure with a bound ligand is known. Antibody: its Gene Ontology location is reachable by antibodies, with high confidence; UniProt predicts a signal peptide or a membrane-spanning region. PROTAC: a small molecule that binds it is known.
Target class: Enzyme; Hydrolase
Gene: Protein-coding gene on chromosome 6 (46,793,368 to 46,839,801, forward strand). Ensembl gene ENSG00000112818.
Subcellular location: Membrane
Gene Ontology:
Molecular function: metallodipeptidase activity; metallopeptidase activity; protein binding; metalloendopeptidase activity; zinc ion binding
Biological process: epidermal growth factor receptor ligand maturation; signaling receptor ligand precursor processing; proteolysis
Cellular component: extracellular exosome; meprin A complex; plasma membrane; extracellular region; membrane
Genetic constraint (gnomAD): Loss-of-function variants: 42 observed, 61.56 expected, observed/expected ratio (o/e) 0.68, 90% interval 0.53 to 0.88. The upper end of that interval is the gene's LOEUF score, 0.88, which puts it in group 3 of 6, group 1 being the genes least tolerant of losing a copy. Missense variants: 737 observed, 783.92 expected, observed/expected ratio (o/e) 0.94, 90% interval 0.88 to 1. Synonymous variants: 287 observed, 299.4 expected, observed/expected ratio (o/e) 0.96, 90% interval 0.87 to 1.06.
Homologues: Orthologues: macaque MEP1A (96% identical), chimpanzee MEP1A (95% identical). Paralogues in human: MEP1B (39% identical), CUBN (16% identical), TLL1 (15% identical), TLL2 (15% identical), BMP1 (15% identical), CNTNAP5 (13% identical), F5 (13% identical), CNTNAP4 (13% identical), CNTNAP2 (12% identical), F8 (12% identical), CNTNAP3B (12% identical), CNTNAP3 (12% identical), and 23 more.
Diseases named in the same sentence as MEP1A in open-access papers:
MEP1A is named in the same sentence as 30 diseases in open-access papers, as found by Europe PMC text mining. Sharing a sentence is not in itself a finding about the gene and the disease. The quoted sentences say what the papers report.
colorectal cancer (7 papers, 2016 to 2025). A primary or metastatic malignant neoplasm that affects the colon or rectum. "For example, in hepatocellular carcinoma and colorectal cancer, a small eccDNA originating from the meprin A subunit alpha (MEP1A) was validated in plasma samples." (PMID 40934041, 2025). "An experimental research of the gene expression profiles related to colorectal cancer shows that MEP1A is a prognostic biomarker and promotes proliferation and invasion of cancer." (PMID 37100777, 2023). "MEP1A is not only involved in the progression of hepatocellular carcinoma and colorectal cancer but was also used as a prognostic biomarker." (PMID 37649244, 2023). "In this report, we explored the clinical significance and functional relevance of the expression of meprin-ɑ (MEP1A) in colorectal cancer (CRC)." (PMID 27378469, 2016).
hepatocellular carcinoma (7 papers, 2020 to 2025). A malignant tumor that arises from hepatocytes. "Extensive MEP1A expression has been linked to hepatocellular carcinoma, promoting the migration and infiltration of cancer cells." (PMID 40762738, 2025). "MEP1A has been identified as a poor prognostic factor in hepatocellular carcinoma and has been reported to be involved in invasion and metastasis." (PMID 39158384, 2024). "Abnormal MEP1A expression has been implicated in several cancers, including CRC, breast cancer, and hepatocellular carcinoma." (PMID 36793075, 2023). "MEP1A is predicted to have metalloendopeptidase activity, is involved in proteolytic processes, is localized in extracellular vesicles, and promotes the progression of hepatocellular carcinoma." (PMID 40427044, 2025).
colitis (4 papers, 2014 to 2023). Inflammation of the colon. "Mep1A-deficient mouse models are more susceptible to chemically induced colitis, in accordance with the decreased expression of MEP1A in UC patients." (PMID 37875976, 2023). "The expression of MEP1A is decreased in patients with active UC and experimental mice models with Mep1A-deficiency are more susceptible to chemically induced colitis." (PMID 25593900, 2014). "Furthermore, mep1a/b−/− mice suffer from a more severe disease progression in DSS-induced colitis than wild-type mice." (PMID 37000885, 2023).
inflammatory bowel disease (3 papers, 2020 to 2022). A spectrum of small and large bowel inflammatory diseases of unknown etiology. "A number of mutations in Mep1A including in its MATH domain are linked to inflammatory bowel disease." (PMID 36422153, 2022). "MEP1A has been identified as a genetic susceptibility factor for inflammatory bowel disease." (PMID 33244381, 2020).
pancreatic cancers (3 papers, 2021 to 2024). "MEP1A has been implicated in kidney, colorectal and pancreatic cancers." (PMID 34359689, 2021). "In pancreatic cancer, MEP1A levels have been reported to significantly increase in the urine of patients with PDACs compared to that with chronic pancreatitis, and its expression has been associated with angiogenesis." (PMID 39158384, 2024). "Despite the established importance of MMP9 in mediating invasiveness and metastasis in pancreatic cancer, the role of MEP1A in PDACs remains unclear." (PMID 39158384, 2024). "One prior study showed potential for MEP1A with lower membranous staining in MOC compared with pancreatic cancers; however, in our cohort, the mean mRNA expression was higher in MOC compared with upper GI tumors, including in comparison with pancreatic tumors alone (P = 0.006)." (PMID 36222710, 2022). "The heightened expression of dihydropyrimidine dehydrogenase (DPYD) in pancreatic cancer not only accelerates pyrimidine degradation but also stimulates cell proliferation and invasiveness, accompanied by the upregulation of MMP9 and MEP1A." (PMID 39158384, 2024).
Alzheimer disease (2 papers, 2023 to 2025). A progressive, neurodegenerative disease characterized by loss of function and death of nerve cells in several areas of the brain leading to loss of cognitive function such as memory and language. "Closely related to meprin α (MEP1A), both proteins have been implicated in inflammatory disorders, Alzheimer’s disease, kidney disease and cancer." (PMID 36349687, 2023).
liver disease (2 papers, 2021 to 2023). "For the investigation of KLK6 and MEP1A tissue expression, liver biopsy sections from five HCC, four benign liver disease including cirrhosis and five cases with normal liver tissue without disease were selected from the Arden tissue bank." (PMID 34359689, 2021). "However, the same group showed that MEP1A was found to be elevated following analysis of the HCC tissues using quantitative real-time polymerase chain reaction compared with matched adjacent nonneoplastic tissues and non-malignant liver disease tissues." (PMID 34359689, 2021).
atherosclerosis (1 paper, 2023). A disease characterized by the build-up of fatty material and calcium deposition in the arterial wall resulting in partial or complete occlusion of the arterial lumen. "Capn1/2 and Mep1a activation has been identified as a key driver of inflammation in other diseases of inflammation and remodeling, such as atherosclerosis and cardiac disease." (PMID 37340062, 2023).
Cirrhosis (1 paper, 2021). A chronic disorder of the liver in which liver tissue becomes scarred and is partially replaced by regenerative nodules and fibrotic tissue resulting in loss of liver function. "The IHC suggests that KLK6 increase with cirrhosis and HCC while MEP1A decrease in cirrhosis and HCC." (PMID 34359689, 2021). "The gradient staining confirmed the predicted activity, showing that KLK6 increases with cirrhosis and HCC, and MEP1A decreases in cirrhosis and HCC." (PMID 34359689, 2021). "For MEP1A, there was an absence of staining in cirrhosis and HCC, whereas it was mildly present in normal liver tissue." (PMID 34359689, 2021).
diabetic nephropathy (1 paper, 2025). "Meprin A subunit alpha, a membrane‐bound oligomeric metalloproteinase, has been reported to be associated with kidney damage; this study focuses on diabetic patients, which may be related to diabetic nephropathy and requires further validation." (PMID 41476994, 2025).
glioma (1 paper, 2023). A benign or malignant brain and spinal cord tumor that arises from glial cells (astrocytes, oligodendrocytes, ependymal cells). "For the sake of clarifying the expression of BMGs in glioma, this study screened 9 BMGs that were upregulated in glioma (FBN2, FREM3, Lamb4, MEP1A, MMP1, MMP7, OPTC, EVA1A, and ADAMTS20) from TCGA -GTEX expression matrix." (PMID 37335645, 2023).
mucinous ovarian carcinomas (1 paper, 2020). An invasive malignant neoplasm that arises from the ovary and is characterized by the presence of malignant epithelial cells that contain intracytoplasmic mucin and may resemble the epithelial cells of the endocervix or gastrointestinal tract. "The study revealed that while galectin-4 expression was relatively consistent in different tumor tissues, the expression of membranous MEP1A in mucinous ovarian carcinomas (MOCs) was significantly lower than that in gastrointestinal cancer." (PMID 33157989, 2020). "It suggested that MEP1A could be helpful to differentiate primary and secondary ovarian mucinous adenocarcinoma." (PMID 33157989, 2020).
nephritis (1 paper, 2020). Inflammation of renal tissue. "The following potential proteases for the different CKD aetiologies were identified: ADPKD (MMP7), MCD (CTSB, CTSD, CTSE, MEP1A, MMP7, PGA3), MGN (MMP3, MMP7, MMP9, MMP13, MMP14), IgAN (MMP7), FSGS (MMP3, MMP7), vasculitis (PGA3), nephritis (MMP7, MMP9), nephrosclerosis (MMP7), and DKD (MMP9)." (PMID 32427855, 2020).
pancreatic ductal carcinoma (1 paper, 2024). "Clinicopathological characteristics of MEP1A high or low pancreatic ductal carcinoma." (PMID 39158384, 2024).
Stroke (1 paper, 2022). Sudden impairment of blood flow to a part of the brain due to occlusion or rupture of an artery to the brain. "Four of these variants (TPTE rs143510517, MEP1A rs62619974, DDX31 rs142792732, and PATL1 rs79336999) were associated with stroke at p < 1 × 10−10." (PMID 36672803, 2022).
cancer (13 papers, 2014 to 2025). A tumor composed of atypical neoplastic, often pleomorphic cells that invade other tissues. "A previous study in humans highlighted MEP1A as a secretory metalloproteinase capable of cleaving numerous protein substrates, some of which are closely associated with cancer." (PMID 40762738, 2025). "MEP1A expression is differentially associated with colorectal, breast, osteosarcoma, among other cancer types, and pancreatic cell-lines." (PMID 27378469, 2016). "We then focused on the small eccDNAs originated from exons and found that two small eccDNAs were significantly enriched in cancer plasma, including one originated from MEP1A and the other originated from myosin 18b (MYO18B)." (PMID 37649244, 2023). "MEP1A has been considered as a prognostic biomarker and found to promote proliferation and invasion of various cancers." (PMID 37649244, 2023). "MEP1A is a member of the astaxanthin family and critically affects forecasting cancer patient prognosis." (PMID 36497225, 2022). "The network surrounding Il10ra shows that many of them are cancer related, e.g., Reg3g, Aoc1, Mep1a, Irf7, Gas6, B3gnt7, Tap1, Tgm2, and Nos2." (PMID 33396408, 2020). "Meprin alpha (Mep1A) is a secreted metalloproteinase with many substrates relevant to cancer invasion." (PMID 27999200, 2017). "Immunohistochemistry showed that high MEP1A expression in CRC tissues was significantly aligned to other features of the malignant tumor." (PMID 27378469, 2016). "It has been recently reported that MEP1A enzyme exhibits a broad expression pattern, implicating functions in angiogenesis, cancer, inflammation and fibrosis." (PMID 25202906, 2014). "Additional work confirmed that MEP1A plays a significant role in cancer prognosis." (PMID 40934041, 2025). "The findings confirmed that MEP1A plays a significant role in cancer diagnosis." (PMID 40934041, 2025). "The mechanism of MEP1A promoting cancer development may be realized by changing the expression of MMP9, vimentin, and E-cadherin, and participating in the EMT procession." (PMID 37100777, 2023). "We also provide evidence that the metalloprotease MEP1A may represent a downstream effector of CCL14-AS in the cancer cells." (PMID 36793075, 2023). "MEP1A has been explored as a prognostic marker for patients with HCC, especially early HCC, and it may play an important role in the progression of HCC by promoting migration and invasion of cancer cells." (PMID 33828988, 2021).
tumor (12 papers, 2016 to 2025). "The immunohistochemical analysis was conducted on tissue samples of 394 patients who were with HCC, and the results showed that the positive expression of MEP1A in tumor cells was an important risk factor affecting survival after radical resection." (PMID 33157989, 2020). "Kaplan-Meier analysis with a log rank test for overall survival (OS) determined possible associations between tumor expression of MEP1A and patient survival." (PMID 27378469, 2016). "Several parameters were associated with enhanced MEP1A expression including tumor size (P = 0.023), staging of CRC by the American Joint Committee on Cancer (AJCC) (P = 0.024), and T (P = 0.032) and N stages (P = 0.001)." (PMID 27378469, 2016). "The six-BMRGs risk score, comprising CD151, CTSA, MMP1, ROBO3, ADAMTS5 and MEP1A, was established for the prediction of clinical prognosis, tumor microenvironment characteristics, and immunotherapy response in HCC." (PMID 39070142, 2024). "Other significantly upregulated genes such as SALL4, FOXM1, MYCN, MEP1A and MYBL2 have also been reported to be significantly elevated in HCC and associated with tumor progression." (PMID 36212481, 2022). "The results will systematically summarize and display the currently collected evidence on the predictive value of MEP1A in different tumor prognosis." (PMID 33157989, 2020). "The purpose of this systematic review was to evaluate the predictive value of MEP1A in tumor prognosis." (PMID 33157989, 2020). "We validated expression of meprin-1α encoded by the MEP1A gene, which strongly increases in tumors on the CAM, in a HBL patient tumor by immunohistochemistry." (PMID 29662633, 2018). "The mRNA and protein expression levels of MEP1A in tumor specimens obtained from CRC patients was determined by quantitative real-time PCR and Western blot assay and comparatively paired with adjacent mucosa that presented as normal tissue." (PMID 27378469, 2016). "Patients that displayed high levels of MEP1A expression in their tumor had a poorer OS (P < 0.001) than did patients with low levels of MEP1A expression." (PMID 27378469, 2016). "High expression of MEP1A was significantly correlated with tumor size (P = 0.023), AJCC stage (P = 0.024), T stage (P = 0.032) and N stage (P = 0.001)." (PMID 27378469, 2016). "As anticipated, down-regulation of MEP1A suppressed both subcutaneous and metastatic tumor formation in nude mice." (PMID 27378469, 2016). "Using a univariate analysis in the Cox proportional hazards model, a decreased OS was associated with the following characteristics: tumor location, AJCC stage, LNM stage, distant metastasis, vascular invasion and the expression of MEP1A and E-cadherin." (PMID 27378469, 2016). "In this immunohistochemical study, we found that high MEP1A expression correlated negatively with E-cadherin expression, suggesting that MEP1A is involved in tumor migration and invasion." (PMID 27378469, 2016). "The mean MEP1A mRNA expression levels in tumor tissue specimens was significantly higher than which in paired adjacent normal mucosal specimens (i.e., 1.04 ± 0.04 vs. 0.49 ± 0.03, respectively at P < 0.001 by Student’s t-test)." (PMID 27378469, 2016). "Subsequent Western blotting analysis confirmed that the protein expression levels of MEP1A were also higher in CRC specimens than were found in the matched adjacent non-tumor tissues (i.e., 1.04 ± 0.05 vs. 0.47 ± 0.03 at P < 0.001, Student’s t-test)." (PMID 27378469, 2016). "As a protease that is known to cleave extracellular matrix components in vitro, MEP1A may contribute to tumor progression by facilitating migration, invasion, and metastasis of tumor cells." (PMID 36793075, 2023). "Furthermore, subgroup analysis showed that patients with positive MEP1A expression in tumor cells had a worse surgical prognosis compared with patients with negative MEP1A expression in tumor cells." (PMID 33157989, 2020).
tumor (continued). "Conversely, high expression levels of MEP1A and EGFL6 were associated with better overall survival (MEP1A: hazard ratio (HR) = 0.78, 95% CI: 0.62–0.98, log-rank p = 0.033; EGFL6: HR = 0.65, 95% CI: 0.53–0.81, log-rank p < 0.001), suggesting their potential tumor suppressor roles." (PMID 40427044, 2025). "In this study, we will search the English database to collect evidence about the application of MEP1A in tumor prognosis, and plan to conduct a systematic review and meta-analysis based on the extracted data, hoping to provide a reference for the prediction of MEP1A in the field of tumor prognosis." (PMID 33157989, 2020). "Through bioinformatic analysis, we identified four MAM domain-containing genes (EGFL6, MEP1A, MEP1B, and MAMDC2) that showed significant differential expression between tumor and adjacent normal tissues in CRC." (PMID 40427044, 2025). "The expression of CCL20, CD70, PCDH7, DCBLD2, and MMP14 genes were remarkably more elevated within LUAD samples than adjacent non-tumorous tissues, where PIK3R5, RNF144B, BTG2, CD69, and MEP1A genes were the opposite." (PMID 36497225, 2022). "For instance, upregulation of most cathepsins, CAPN1 and 2, MEP1A, and MMP25, exhibited a major correlation with poor prognostic features such as recurrence, perineural invasion, nodal extracapsular extension, and tumor size." (PMID 33578082, 2021). "We conclude that MEP1A played a functionally crucial role in CRC carcinogenesis, which was particularly evident in terms of tumor proliferation and invasion." (PMID 27378469, 2016). "Moreover, immunohistochemical staining demonstrated MEP1A and MMP9 protein expression within the tumor gland ducts of the xenograft tumors, with a notably higher percentage of the positively stained area observed in AsPC1‐DPYD tumors than in AsPC1‐LacZ tumors." (PMID 39158384, 2024). "At present, some studies have reported that MEP1A has been involved in the diagnosis and prognosis prediction of different kinds of diseases, including tumor and nontumor." (PMID 33157989, 2020). "The results of clinical studies showed that compared with paired adjacent nonneoplastic tissues and nontumor liver tissues, the expression level of MEP1A mRNA in HCC was significant increase in tumor tissue." (PMID 33157989, 2020). "During the course of tumor development we observed a slight but significant decrease of LIN28A stem cell marker typical for HBL and an increase of 3-hydroxy-3-methylglutaryl-CoA synthase 2 HMGCS2 and MEP1A." (PMID 29662633, 2018).
MEP1A also shares sentences with these, for which no sentence is quoted: lymph node metastasis (2 papers); -intestinal inflammation (1); breast carcinoma (1); cardiomyopathies (1); chronic pancreatitis (1); GI tumors (1); kidney damage (1); kidney disease (1); lung carcinoma (1); nephrosclerosis (1); ulcerative colitis (1); vasculitis (1); virus infection (1).